IL1B (interleukin 1 beta)
Diseases named in the same sentence as IL1B in open-access papers (continued):
Sharing a sentence is not in itself a finding about the gene and the disease.
Sepsis (continued). "The concentrations of IL-1β, IL-6, and TNF-α were significantly higher in the sepsis groups than those in the NC group." (PMID 28513569, 2017). "The therapeutic effects of rSj-Cys treatment were associated with the significant reduction of pro-inflammatory cytokines (TNF-α, IL-1β and IL-6) and boost of IL-10 and TGF-β1 cytokines in sera of mice with sepsis." (PMID 28482922, 2017). "Excessive release of inflammatory factors, such as IL-1β, IL-6, and TNF-α, triggered pathophysiological abnormities of sepsis." (PMID 28994737, 2017). "As evidenced by the plasma level of TNF‐α and gene expression of IL‐1β and TNF‐α in the heart, inflammation was developed in the sepsis group." (PMID 28684640, 2017). "The activation of NF-κB (p65) was proved to play important roles in the development and progression of sepsis through enhancing the transcription of various pro-inflammatory cytokines including TNF-α, IL-1β, IL-6." (PMID 28430592, 2017). "The sepsis patients exhibited significantly higher plasma concentrations of TNF-α, IL-6 and IL-1β compared with the healthy controls." (PMID 28472164, 2017). "Elevated levels of cytokines, such as IL-1β, TNF-α, and IL-6, have been observed in the brain parenchyma and cerebrospinal fluid after sepsis." (PMID 28236057, 2017). "In a murine CLP model of polymicrobial sepsis, IL-17A from γδT cells was detected, but its depletion led to a decrease in bacteremia and reductions in systemic proinflammatory cytokines (TNF-α, IL-1β, and IL-6) and chemokines." (PMID 27334720, 2016). "Similar to the serum results, the concentration of IL-6, TNF-α, IL-1β and IL-1α in the colonic wall rose significantly following CLP-induced sepsis." (PMID 27044016, 2016). "In sepsis, cytokines like TNF-α, interleukin-1 beta (IL-1β) and IL-6 which are released after infection, play an important role in the inflammatory process." (PMID 27150961, 2016). "Since the essence of sepsis is the inflammatory reactions, we detected the productions of inflammatory cytokines, such as TNF-α, IL-1β, and IL-6, in kidney tissue by ELISA." (PMID 26904148, 2016). "LPS can promote overexpression of proinflammatory cytokines including IL-6, IL-1β, and TNF-α, which was involved in subsequent sepsis." (PMID 28042205, 2016). "During the early stages of sepsis, the body is at a proinflammatory stage accompanied by the release of a large number of proinflammatory cytokines such as TNF-α, IL-1β, and IL-6." (PMID 27195281, 2016). "Systemic LPS injection results in a strong and immediate increase of several pro-inflammatory cytokines such as IL-6, TNF and IL-1β compared to a prolonged cytokine increase after CLP which resembles the progression and characteristics of human sepsis." (PMID 27437704, 2016). "Patients with sepsis had a reduced capacity to release TNF-α and IL-1β upon LPS stimulation compared to healthy controls." (PMID 27737683, 2016). "In TNF-α induced mouse systematic sepsis model, RIP3-KO mice recovered from hypothermia and survived longer, which was partly by reducing DAMPs and IL-1β, IL-6." (PMID 27195494, 2016). "Pharmacological inhibition of the PKM2–EIF2AK2 pathway reduced the release of both early (for example, IL-1β) and late (for example, HMGB1) proinflammatory mediators and protected animals against lethal sepsis." (PMID 27779186, 2016). "The inflammatory cytokines IL-6, IL-1β, and TNF-α have been well documented to increase mortality in sepsis." (PMID 27009867, 2016). "In the early stages of sepsis, the production of NO was decreased and the release of TNF-α, IL-6, and IL-1β was inhibited by citrulline supplementation." (PMID 27195281, 2016). "In our sepsis model, dendritic cells expressing TLR2 were required for a robust IL-17A response, which was mediated by IL-1β and IL-23." (PMID 26039416, 2015). "In our study, pro-inflammatory cytokines (TNF-α and IL-1β) and WBC count were detected for the evaluation of the severity of sepsis in each group." (PMID 26149595, 2015).
Sepsis (continued). "To evaluate the neuroinflammation in the sepsis survivors, we measured TNF-α, IL-1β, IL-6, and IL-10 expressions in the PFC and hippocampus." (PMID 26416717, 2015). "In this study, we used a mice model of lipopolysaccharide (LPS)-activated sepsis, mimicking what occurs in clinical sepsis, to investigate the effects of Dex and α-Bgt on spleen TNF-α, IL-6, and IL-1β release in vivo." (PMID 26702389, 2015). "This latter observation contrasts with the increased IL1β levels in this study’s SIRS group and reports that ESM-1 increase was a marker of respiratory failure during sepsis." (PMID 26263001, 2015). "Our results showed that rhein treatment decreased the level of TNF-α and IL-1β in the two sepsis models in vivo, which suggest that the protection of rhein against septic-AKI are related to down regulation of TNF-α and IL-1β level." (PMID 26149595, 2015). "Both IL-1β and TNF-α appear to play important roles in endoxemia/sepsis-induced myocardial dysfunction." (PMID 25216263, 2014). "Clinical and experimental studies have shown that LPS-induced sepsis can lead to a rapid simultaneous secretion of two functionally heterogeneous groups of cytokines: pro-inflammatory cytokines (e.g., TNF-α, IL-1β and IL-6) and anti-inflammatory (e.g., IL-10)." (PMID 24904237, 2014). "In addition to the processing of IL-1β, caspase-1 may execute apoptosisduring sepsis." (PMID 25412304, 2014). "Meanwhile, several studies demonstrate that macrophages also produce IL-1β, TNF-α, and IL-6 during sepsis." (PMID 23675299, 2013). "The pathogenesis of sepsis involves a complex process of cellular activation at multiple levels resulting in release of pro-inflammatory cytokines such as TNF-α, IL-1β, high-mobility group box 1(HMGB1) and anti-inflammatory cytokines, such as IL-10." (PMID 23497622, 2013). "Taken together, these data suggest that NOD2-mediated IL-1β-dependent and/or IL-1β-independent IL-10 production enhances C5a generation by suppressing CD55 expression on neutrophils, thereby aggravating sepsis." (PMID 23675299, 2013). "Nod2−/− mice showed lower levels of C5a, IL-10, and IL-1β in serum and peritoneum, but higher survival rate during CLP-induced sepsis compared to wild type mice." (PMID 23675299, 2013). "Therefore, the NOD2-mediated IL-1β-IL-10 regulatory loop in neutrophils helps enhancement of C5a generation, which may partially account for the different kinetics of pro- and anti-inflammatory cytokines in sepsis." (PMID 23675299, 2013). "In acute injuries and diseases such as burns, surgeries, and sepsis, the contents of TNF-α, IL-1β, and IL-6 significantly increase." (PMID 23586067, 2013). "In early studies, the efficacy of anti-TNF-α and IL-1 receptor-antagonist therapies in human sepsis were disappointing, partly because TNF-α and IL-1β were released early in the development of sepsis, thereby limiting the effect of such therapies." (PMID 23497622, 2013). "TAT complex levels were increased in culture supernatants from sepsis neutrophils and control neutrophils treated with sepsis serum or TNF-α, IL-1β and G-CSF (Fig. 4iii)." (PMID 23029002, 2012). "In our study, treatment of myrrh reduced expression of IL-1β, IL-6, and TNF-α in serum and liver during CLP-induced sepsis." (PMID 21826187, 2012). "The up-regulation of TNF-α, IL-1α, IL-1β, CXCL-10, SOCS3, IL-10 at 1 and 2 h in the present study was similar to that observed in blood profiles of sepsis patients at early stages." (PMID 23009705, 2012). "Cardiomyocyte (CMs) isolated from wild mice undergoing sepsis produced high levels of IL-6, TNF-α, IL-1β, MIP-1α, MIP-2, MCP-1, and KC, while CMs from C5L2-deficient mice secreted significant low level of the inflammatory mediators." (PMID 23233853, 2012). "The main inflammatory mediators that contribute to myocardial depression in sepsis include interleukins (IL-2, IL-4, IL-6, IL-8, and IL-10), gamma interferon (IFN-γ), TNF-α, IL-1β, and C5a." (PMID 22482045, 2012).
Sepsis (continued). "Sepsis induced by CLP resulted in a significant up-regulation of cerebral expression of TNF-α and IL-1β mRNA (n = 5)." (PMID 23236515, 2012). "“Cardiosuppressive cytokines,” the definition of which is based on their ability to disrupt normal contractile function of normal CMs, have been described in patients with sepsis, and include IL-6, TNF-α, and IL-1β." (PMID 23233853, 2012). "They showed that TNF, IL1-β, CD3D and PRF1 gene expressions were significantly different in patients who developed postoperative sepsis in comparison with patients who recovered uneventfully." (PMID 22027436, 2011). "In a mouse model of sepsis, IL-32 was shown to potentiate peritonitis-induced elevations in serum levels of TNF-α and IL-1β, and overexpression of the IL-32β isoform led to reduced time to death." (PMID 21649914, 2011). "This is accompanied by a reduction in the pro-inflammatory mediators IL-1β, IL-6 and TNF-α, as well as a decrease in NF-kB binding activity, thereby inhibiting an overwhelming inflammation response to sepsis." (PMID 19196475, 2009). "Theaim of this study is to determine serum IL-1β, IL-6, IL-8, and TNF-α levels inneonatal sepsis at the time of diagnosis and after therapy and to show themeaningful on the follow up." (PMID 18274637, 2007). "Elevated serum IL-1β, IL-6, IL-8, and TNF-α levels have beenfound in both the neonatal and adult sepsis." (PMID 18274637, 2007). "A study of sepsis-induced muscle atrophy in a mouse model revealed that the NLRP3 inflammasome participates in regulating muscle atrophy, as NLRP3-KO mice exhibited less severe muscle atrophy and lower serum IL-1β levels than WT mice." (PMID 41399377, 2026). "Consistent with our in vivo sepsis lung tissue data, Fer-1 significantly attenuated LPS induced expression of proinflammatory cytokines IL-1β and IL-6, but not TNFα, as well as the chemokine CXCL1 and chemokine receptor CCR5." (PMID 41518848, 2026). "Despite the remarkable success in preclinical models, most anti-inflammatory therapies targeting cytokine storms (such as anti-TNF-α, anti-IL-1β, and anti-endotoxin agents) have failed to significantly reduce mortality in large Phase 3 sepsis clinical trials." (PMID 41521316, 2026). "Sepsis patients with a history of severe COVID-19 exhibited significantly higher IL-1β, IL-6, and IL-17 levels compared to those in the non-severe COVID-19 H group (P = .002, P <.001, and P <.001, respectively)." (PMID 41305706, 2025). "Mechanistically, microbial translocation in sepsis results in the activation of hepatic Kupffer cells through TLR4 signaling, which triggers downstream NF-κB activation and induces the release of proinflammatory cytokines such as TNF-α and IL-1β." (PMID 41268545, 2025). "Furthermore, coincubation of OLA@MΦ NPs released from the capsules with IL‐1β, IL‐6, TNF‐α, and LPS, key mediators of the cytokine storm during sepsis, showed dose‐dependent binding of the NPs to these cytokines." (PMID 39836501, 2025). "Furthermore, the MIF inhibitor also mitigated the effects of CSN6 on the mRNA expression levels of pro-inflammatory cytokines IL-1β, IL-6, TNF-α, and collagen I/III in macrophages in an in vitro sepsis model (n = 6 per group)." (PMID 40595050, 2025). "Sepsis also triggers a massive release of pro-inflammatory cytokines, such as interleukin-6 (IL-6), tumor necrosis factor-alpha (TNF-α), and interleukin-1 beta (IL-1β), as well as reactive oxygen species (ROS)." (PMID 40563999, 2025). "Further investigations have revealed that during sepsis, macrophage autophagy hinders the activation of the NLRP3 inflammasome by targeting the lysosome responsible for degrading IL-1β, thereby diminishing the secretion of IL-1β." (PMID 40918153, 2025). "Studies have shown that ursolic acid may prevent sepsis–induced acute kidney injury in mice by inhibiting reactive oxygen species and inflammatory cytokines in the kidneys, including TNF–α, IL–1β, and IL–6." (PMID 40005889, 2025).
Sepsis (continued). "Sepsis can also induce severe oxidative stress in the kidneys, as evidenced by elevated levels of MDA, a key end product of lipid peroxidation, and is accompanied by marked upregulation of inflammatory cytokines including IL-1β and TNF-α." (PMID 40993513, 2025). "Sepsis triggers a systemic inflammatory response syndrome (SIRS), characterized by the release of pro-inflammatory cytokines such as tumor necrosis factor-alpha (TNF-α), interleukin-6 (IL-6), and interleukin-1β (IL-1β)." (PMID 41425961, 2025). "Notably, HLA-DRA, IL1B, and CD86 were prominently elevated in Microglia 2 from sepsis patients, while P2RY12 and TREM2 were reduced, further supporting a pro-inflammatory shift." (PMID 41030458, 2025). "Si-CSN6 reduced IL-1β, IL-6, and TNF-α levels in an in vitro sepsis model (n = n= 6 per group)." (PMID 40595050, 2025). "Many of the immunological markers discussed in this review, such as interleukin-6 (IL-6), tumor necrosis factor-alpha (TNF-α), interleukin-1 beta (IL-1β), and myeloperoxidase (MPO), have been extensively studied in the contexts of sepsis, cardiovascular disease, or general critical illness." (PMID 40710793, 2025). "A deeper understanding of this mechanism may inform the development of precision therapies targeting key cytokines—such as IL-1β and IL-18—or downstream effectors to mitigate cytokine storms in severe AOSC patients with sepsis and reduce mortality." (PMID 41438472, 2025). "Similarly, sepsis involves massive pro-inflammatory cytokine release (e.g., TNF-α, IL-1β, IL-6), triggering systemic inflammatory responses and tissue injury." (PMID 40657502, 2025). "This suggests that the shared DEGs may be affecting sepsis and ALL patients by influencing interleukin-1 beta production." (PMID 38123749, 2025). "Circulating EVs notably exacerbate the inflammatory response to sepsis in both serum and lung tissue by enhancing the production of proinflammatory factors such as tumor necrosis factor-α (TNF-α), interleukin-6 (IL-6), and interleukin-1β (IL-1β)." (PMID 39967672, 2025). "We confirmed substantially lower MCSF, TNFR2 and IL-1β levels in the plasma from heatstroke patients, although the differences from sepsis patients did not achieve statistical significance." (PMID 40084252, 2025). "The previous study of our research group confirmed that DCHD significantly could reduce serum inflammatory factor levels (e.g., IL-1β, TNF-α, IL-6) in rats with sepsis induced by cecal ligation and puncture." (PMID 41378216, 2025). "Our results indicated that acute abdomen III could lower blood concentrations of IL-6, IL-1β, and TNF-α in the sepsis model, consistent with previous findings." (PMID 40582762, 2025). "In sepsis, SIRT1 accumulates at IL‐1β/TNF‐α promoters with NAD+‐enhanced H3K16 deacetylation." (PMID 41208649, 2025). "Gene expression of cytokines IL-1β (Il1b) and IL-6 (Il6), but not Tnf (Tnf) was upregulated in acute and prolonged sepsis." (PMID 39821755, 2025). "The primary outcomes assessed were levels of inflammatory markers such as IL-1β, IL-6, IL-8, IL-10, CRP, PCT, and TNF-α, providing a comprehensive overview of the effectiveness of the combined therapy on inflammatory responses in sepsis patients." (PMID 40667510, 2025). "A recent study further showed that luteolin (20 mg/kg) inhibits the AKT1/nitric oxide synthase 2/cathepsin G (AKT1/NOS2/CTSG) axis, thereby blocking caspase-11 and GSDMD activation, leading to reduced IL-1β and TNF-α release, thus mitigating sepsis-induced pulmonary injury." (PMID 41394141, 2025). "Similarly, numerous reports note elevation in serum concentrations of IL-1β, IL-6, IL-8, and TNF-α between neonatal individuals with sepsis and the corresponding control cohorts." (PMID 38510969, 2024). "Additionally, the expression of IL1β, TNFα, and IL6 in BALF from FGF2 KO mice was higher than that in WT mice in the sepsis model." (PMID 39436561, 2024).
Sepsis (continued). "Once formed, the NLRP3 inflammasome activates caspase-1, which subsequently mediates the cleavage of pro-IL-1β and pro-IL-18 and the secretion of their bioactive forms, important players in the systemic inflammation and cardiac dysfunction (and MOF) during sepsis." (PMID 39559354, 2024). "FITC, IL-1β, TNF-a and D-lactic acid levels were significantly elevated in the sepsis group." (PMID 39026673, 2024). "An amount of production of pro-inflammatory cytokines such as TNF-α, IL-1β, and IL-8 are relevant to tissue injuries, sepsis, and noninfectious systemic inflammatory response syndrome in dogs." (PMID 38535325, 2024). "During the hyperinflammatory phase of sepsis, macrophages play a crucial role in monitoring the infection through their ability to phagocytose bacteria, present antigens, and produce significant amounts of cytokines such as TNF-α, IL-6, and IL-1β." (PMID 38799158, 2024). "Interestingly, the repressive mark H3K9me2 was significantly enriched in TNFA, IL-1B, CXCL8, and IL-17 gene promoters at 1 dpb in patients who developed sepsis." (PMID 39768289, 2024). "The cecal gene expression of IL-6, IL-1β, TNF-α, IL-17A, IL-22, and CRAMP (homologue of human cathelicidin LL-37) was significantly elevated in mice with gut-derived P. aeruginosa sepsis." (PMID 38790988, 2024). "Sepsis is marked by an initial and intense systemic inflammatory response syndrome (SIRS), commonly referred to as a cytokine storm, characterized by overexpression of inflammatory mediators like IL-1β, IL-6, and IL-8." (PMID 38397855, 2024). "Another study investigated the role of FGD5-AS1 in sepsis and LPS-induced inflammation and showed that FGD5-AS1 overexpression increased AQP1 and decreased miR-133a-3p expression, subsequently reducing inflammatory cytokines such as TNF-α, IL-6 and IL-1β." (PMID 39544938, 2024). "We found that NLRP6-driven IL-18 but not IL-1β contributes to sepsis-induced lymphocyte death, which were found to be crucial for host defense." (PMID 38720893, 2024). "The three major pro-inflammatory cytokines TNF-α, IL-1β and IL-6 were not specific for sepsis and their primary role as biomarkers of sepsis appears to be prognostic rather than diagnostic." (PMID 38643461, 2024). "However, drugs targeting inflammatory mediators, like IL-1β, TNF-α, or TLR, to suppress inflammation are ineffective in improving survival in sepsis patients." (PMID 38558800, 2024). "In our in vivo model of polymicrobial sepsis, the absence of PLXNC1 resulted in a more severe inflammatory immune response, markedly with higher levels of IL-1β and IL-18, the hallmark cytokines of inflammasome activity." (PMID 39169397, 2024). "Moreover, when evaluated in vivo on mice sepsis model, both nanosystems have demonstrated a superior effect over the uncoated AMPNP regarding the reduction in serum cytokines (IL-1β, TNF-α, and IL-6) levels and inflammatory cells tissue infiltration." (PMID 38637839, 2024). "Furthermore, the specific deficiency of TREM2 in macrophages decreased the production of IL-6, IL-1β, and TNF-α in the lung of sepsis mice." (PMID 39405126, 2024). "Additionally, the control group showed decreased intestinal barrier permeability, lower plasma levels of inflammatory factors (IL-1β and TNF-α), and heightened protein expression of mechanical barrier markers like ZO-1 in contrast to the sepsis feces group." (PMID 39026673, 2024). "During sepsis, the presence of LPS can trigger the TLR4 signaling pathway, leading to the translocation of NF-κB, subsequently impacting the expression of pro-inflammatory cytokines, such as IL-1β and interleukin-6 (IL-6)." (PMID 39677961, 2024). "Additionally, the peritoneal lavage of all sepsis groups exhibited increased PGE2, IL-27, IL-1β, and IL-12p70 levels." (PMID 39281680, 2024). "An increase in the level of IL-1β in non-survivors suggests a correlation between IL-1β expression and sepsis outcome." (PMID 38255822, 2024).